ECSIT (ECSIT signaling integrator)
Description:
Adapter protein that plays a role in different signaling pathways including TLRs and IL-1 pathways or innate antiviral induction signaling. Plays a role in the activation of NF-kappa-B by forming a signal complex with TRAF6 and TAK1/MAP3K7 to activate TAK1/MAP3K7 leading to activation of IKKs. Once ubiquitinated, interacts with the dissociated RELA and NFKB1 proteins and translocates to the nucleus where it induces NF-kappa-B-dependent gene expression. Plays a role in innate antiviral immune response by bridging the pattern recognition receptors RIGI and MDA5/IFIT1 to the MAVS complex at the mitochondrion. Promotes proteolytic activation of MAP3K1. Involved in the BMP signaling pathway. Required for normal embryonic development (By similarity). As part of the MCIA complex, involved in the assembly of the mitochondrial complex I.
Synonyms: SITPEC
Tractability: PROTAC: UniProt records ubiquitination sites on it; ubiquitination databases record sites on it; its protein half-life has been measured.
Gene: Protein-coding gene on chromosome 19 (11,505,927 to 11,530,564, reverse strand). Ensembl gene ENSG00000130159.
Subcellular location: Cytoplasm; Nucleus; Mitochondrion
Subcellular location (Human Protein Atlas): Nucleoplasm; Cytosol
Pathways (Reactome):
Immune System: MyD88 cascade initiated on plasma membrane; MyD88:MAL(TIRAP) cascade initiated on plasma membrane; TRAF6 mediated induction of NFkB and MAP kinases upon TLR7/8 or 9 activation
Metabolism: Complex I biogenesis
Gene Ontology:
Molecular function: enzyme inhibitor activity; molecular adaptor activity; protein binding; protein-macromolecule adaptor activity
Biological process: mitochondrial respiratory chain complex I assembly; toll-like receptor 4 signaling pathway; cell surface receptor protein serine/threonine kinase signaling pathway; innate immune response
Cellular component: cytoplasm; cytosol; mitochondrial complex I intermediate assembly complex; mitochondrion; nucleoplasm; nucleus; mitochondrial inner membrane
Genetic constraint (gnomAD): Loss-of-function variants: 32 observed, 41.62 expected, observed/expected ratio (o/e) 0.77, 90% interval 0.58 to 1.03. The upper end of that interval is the gene's LOEUF score, 1.03, which puts it in group 4 of 6, group 1 being the genes least tolerant of losing a copy. Missense variants: 542 observed, 603.37 expected, observed/expected ratio (o/e) 0.9, 90% interval 0.84 to 0.96. Synonymous variants: 231 observed, 244.43 expected, observed/expected ratio (o/e) 0.95, 90% interval 0.85 to 1.05.
Homologues: Orthologues: chimpanzee ECSIT (99% identical), macaque ECSIT (88% identical), dog ECSIT (79% identical), pig ECSIT (77% identical), rabbit ECSIT (76% identical), mouse Ecsit (74% identical), rat Ecsit (73% identical), guinea pig ECSIT (71% identical), zebrafish ecsit (47% identical), tropical clawed frog ecsit (45% identical), Drosophila melanogaster ECSIT (29% identical), Caenorhabditis elegans Y17G9B.5 (24% identical).
Diseases named in the same sentence as ECSIT in open-access papers:
ECSIT is named in the same sentence as 18 diseases in open-access papers, as found by Europe PMC text mining. Sharing a sentence is not in itself a finding about the gene and the disease. The quoted sentences say what the papers report.
cardiac hypertrophy (2 papers, 2021 to 2025). "We show that subthreshold levels of hECSIT contribute to cardiac disease as revealed by the manifestation of cardiac hypertrophy in ECSIT+/+ mice and the association of low levels of hECSIT with myocardial hypertrophy and cardiac fibrosis in human cohorts." (PMID 34032637, 2021). "This study not only examined how the murine ~42‐kDa ECSIT is encoded, its tissue‐ and cell‐specific expression, and its localization, but also highlighted the significance of ECSIT‐X4 up‐regulation in pressure overload‐induced cardiac hypertrophy." (PMID 39746855, 2025). "Interestingly such impaired complex I activity was also observed in younger 10-week-old ECSIT+/+ mice, suggesting that complex I deficiency may precede the development of cardiac hypertrophy." (PMID 34032637, 2021). "Building on this, we next investigated alterations in ECSIT expression within the mitochondria of mouse hearts under TAC‐induced cardiac hypertrophy." (PMID 39746855, 2025). "Wheat germ agglutinin (WGA) staining of cell membrane proteins allowed for calculation of cardiomyocyte cross-sectional area and confirmed cardiac hypertrophy at the cellular level, in cardiac tissue from ECSIT+/+ mice." (PMID 34032637, 2021). "The compensatory shift to glycolysis clearly did not fully restore the ATP-generating capacity of cardiomyocytes, and in the in vivo setting this likely led to an adaptive cardiac hypertrophy response that we observed in ECSIT+/+ mice." (PMID 34032637, 2021). "Given that hECSIT expression is suppressed in a number of tissues from ECSIT+/+ mice, its direct role in cardiomyocytes was next examined in order to assess if its cell-intrinsic function in cardiac cells may underlie the mitochondrial dysfunction and cardiac hypertrophy observed in ECSIT+/+ mice." (PMID 34032637, 2021). "Low levels of human ECSIT correlate with cardiac hypertrophy and fibrosis." (PMID 34032637, 2021). "Thus reduced expression of hECSIT in human cardiomyocytes that leads to cellular hypertrophy mirrors at a cellular level the cardiac hypertrophy observed in the ECSIT+/+ mice that express low levels of hECSIT." (PMID 34032637, 2021). "Human ECSIT–knockin mice develop early cardiac hypertrophy leading to premature death." (PMID 34032637, 2021). "However, whether an unknown ECSIT isoform exists in cardiac cells and its potential role in regulating mitochondrial function and pathological cardiac hypertrophy has remained unclear." (PMID 39746855, 2025).
heart failure (2 papers, 2021 to 2025). Inability of the heart to pump blood at an adequate rate to meet tissue metabolic requirements. "This study identified a novel transcript variant of ECSIT localized in the mitochondria of adult cardiomyocytes and highlights its potential as a therapeutic target for heart failure." (PMID 39746855, 2025). "While ECSIT+/+ mice showed normal development and maturation into adulthood, we noted that as ECSIT+/+ mice aged, they were subject to premature death from heart failure, with some mice dying at 8 months of age and less than 20% of the mice being viable at 12 months." (PMID 34032637, 2021).
hemophagocytic syndrome (2 papers, 2018 to 2022). "More recently, a hotspot mutation of ECSIT-V140A has also been identified in NKTCL patients with lymphoma-associated hemophagocytic syndrome and poor prognosis." (PMID 30514323, 2018).
amyloid (1 paper, 2023). "Finally, our observations of decreased ECSITCTER phosphorylation in response to Aβ oligomers, coupled to a significantly enhanced NADH-dehydrogenase CI activity, further suggests that ECSIT plays a role as a molecular link between mitochondrial bioenergetics and early amyloid pathology." (PMID 38086790, 2023).
cardiomyopathy (1 paper, 2021). A disease of the heart muscle or myocardium proper. "However, mutations in another factor, ACAD9, which also associates with NDUFAF1 and ECSIT, appear to be a relatively common cause of complex I deficiency presenting as cardiomyopathy and/or exercise intolerance." (PMID 34032637, 2021).
colorectal cancer (1 paper, 2023). A primary or metastatic malignant neoplasm that affects the colon or rectum. "It is also shown that the expression of ECSIT is positively correlated with the survival of patients with colorectal cancer." (PMID 37409430, 2023).
dementia (1 paper, 2019). Loss of intellectual abilities interfering with an individual's social and occupational functions. "The mitochondrial and Toll pathway protein ECSIT has been hypothesized to be a disease hub in dementia (Soler‐López, Badiola, Zanzoni, & Aloy, 2012) because it reflects a point of interaction for inflammation and mitochondrial biology." (PMID 31168962, 2019).
hypertrophic cardiomyopathy (1 paper, 2023). A condition in which the myocardium is hypertrophied without an obvious cause. "We have identified an ENU-induced mutation in ECSIT (N209I) that exhibits a profound effect on Complex I component expression and assembly in heart tissue, resulting in hypertrophic cardiomyopathy in the absence of other phenotypes." (PMID 37395010, 2023).
intestinal tumor (1 paper, 2023). "To directly explore the role of ECSIT in intestinal tumor development, we constructed Apcmin/+Ecsitfl/flVillin‐Cre‐ERT2 mice and compared with control Apcmin/+Ecsitfl/fl mice." (PMID 37409430, 2023). "Given that deletion of the ECSIT gene in intestine induced low survival rates in mice, we employed an inducible and conditional knockdown model that allowed for an exploration of the role of ECSIT in intestinal tumor development over a long period of time." (PMID 37409430, 2023).
latent infection (1 paper, 2025). "This study provides the first mechanistic evidence that HBHA, an LTBI-associated antigen, inhibits macrophage autophagy via ECSIT targeting, offering critical insights into early immune evasion during latent infection and highlighting HBHA-ECSIT axis as a potential host-directed therapeutic target." (PMID 41209015, 2025).
myocardial infarction (1 paper, 2025). Gross necrosis of the myocardium, as a result of interruption of the blood supply to the area, as in coronary thrombosis. "In myocardial infarction models, METTL3-mediated m6A modification within microglia activates the TRAF6/ECSIT signaling pathway, induces mitochondrial oxidative stress in PVN neurons, and stimulates sympathetic hyperactivity, thereby contributing to the development of post-MI ventricular arrhythmias." (PMID 41294833, 2025).
infection (4 papers, 2013 to 2025). The state of being infected such as from the introduction of a foreign agent such as serum, vaccine, antigenic substance or organism. "This suggested dual regulatory roles of ECSIT, as evidenced by prior work: 1) maintaining basal autophagy homeostasis via Parkin-dependent mitophagy, and 2) mediating infection-induced autophagy through TRAF6 ubiquitination." (PMID 41209015, 2025). "Furthermore, infection of ECSIT+/+ and WT BMDMs with S. typhimurium showed comparable activation of NF-κB and MAPK pathways and induction of IL-6 and TNF-α." (PMID 34032637, 2021). "The physiological relevance of this limiting aspect was confirmed in an in vivo infection model in which ECSIT+/+ mice, orally infected with Salmonella, demonstrated impaired clearance and increased dissemination to the liver and spleen when compared with WT and ECSIT+/– mice." (PMID 34032637, 2021). "However, BMDMs from ECSIT+/+ mice displayed a tendency toward reduced mROS but not cytosolic ROS (cROS), relative to WT cells, in response to infection by S. typhimurium." (PMID 34032637, 2021).
bacterial infections (3 papers, 2020 to 2024). "Additionally, ECSIT was also located in the mitochondrial complex I, and implicated in complex stability and mitochondrial and cellular reactive oxygen species production during bacterial infection, thus contributing to the bactericidal activity of macrophages." (PMID 35173723, 2022). "However, among the three identified MjTolls, the key receptor responding to bacterial infection remains unknown, as does whether and how shrimp ECSIT participates in Toll signaling transduction." (PMID 35173723, 2022).
cancer (3 papers, 2020 to 2023). A tumor composed of atypical neoplastic, often pleomorphic cells that invade other tissues. "IHC of human CRC sample microarrays also indicated that the levels of ECSIT protein were significantly decreased in tumor tissue, inversely linked to the stages of cancer progression and positively associated with survival rate of patients." (PMID 37409430, 2023). "Furthermore, ECSIT is an adapter protein known to activate the NF-κB signaling pathway, and USP15 is a deubiquitinating enzyme (DUB) responsible for ubiquitin chain cleavage on known substrates, ultimately leading to cancer cell survival." (PMID 35574218, 2022).
tumor (2 papers, 2020 to 2023). "ECSIT was significantly down‐regulated in tumor versus corresponding peri‐tumor tissue, and in tumor versus control tissue." (PMID 37409430, 2023). "Therefore, the use of PPI inhibitors to inhibit the combination of TRAF6 and ECSIT may play a role in tumor suppression." (PMID 32905356, 2020).
ECSIT also shares sentences with these, for which no sentence is quoted: cardiac disease (1 paper); hypertrophy (1); tuberculosis (1).